CELF4 (CUGBP Elav-like family member 4)
Description:
RNA-binding protein implicated in the regulation of pre-mRNA alternative splicing. Mediates exon inclusion and/or exclusion in pre-mRNA that are subject to tissue-specific and developmentally regulated alternative splicing. Specifically activates exon 5 inclusion of cardiac isoforms of TNNT2 during heart remodeling at the juvenile to adult transition. Promotes exclusion of both the smooth muscle (SM) and non-muscle (NM) exons in actinin pre-mRNAs. Activates the splicing of MAPT/Tau exon 10. Binds to muscle-specific splicing enhancer (MSE) intronic sites flanking the alternative exon 5 of TNNT2 pre-mRNA.
Synonyms: CELF-4; BRUNOL4
Tractability: PROTAC: ubiquitination databases record sites on it; its protein half-life has been measured.
Safety:
Unwanted effects reported when the protein is acted on. In parentheses: how it was acted on, where the effect was seen, and who reports it.
adverse cardiovascular events (source: ClinPGx)
Gene: Protein-coding gene on chromosome 18 (37,243,040 to 37,565,994, reverse strand). Ensembl gene ENSG00000101489.
Subcellular location: Nucleus; Cytoplasm
Subcellular location (Human Protein Atlas): Nucleoplasm
Gene Ontology:
Molecular function: pre-mRNA binding; BRE binding; mRNA regulatory element binding translation repressor activity; nucleic acid binding; RNA binding
Biological process: alternative mRNA splicing, via spliceosome; positive regulation of mRNA splicing, via spliceosome; regulation of alternative mRNA splicing, via spliceosome; embryo development ending in birth or egg hatching; germ cell development; mRNA splice site recognition; mRNA splicing, via spliceosome; negative regulation of translation
Cellular component: nucleoplasm; nucleus; ribonucleoprotein complex; cytoplasm
Genetic constraint (gnomAD): Loss-of-function variants: 18 observed, 48.9 expected, observed/expected ratio (o/e) 0.37, 90% interval 0.25 to 0.55. The upper end of that interval is the gene's LOEUF score, 0.55, which puts it in group 2 of 6, group 1 being the genes least tolerant of losing a copy. Missense variants: 450 observed, 650.85 expected, observed/expected ratio (o/e) 0.69, 90% interval 0.64 to 0.75. Synonymous variants: 258 observed, 253.39 expected, observed/expected ratio (o/e) 1.02, 90% interval 0.92 to 1.13.
Homologues: Orthologues: chimpanzee CELF4 (100% identical), rat Celf4 (99% identical), macaque CELF4 (99% identical), mouse Celf4 (99% identical), guinea pig CELF4 (94% identical), tropical clawed frog celf4 (93% identical), pig CELF4 (93% identical), dog CELF4 (92% identical), rabbit CELF4 (91% identical), zebrafish celf4 (83% identical), Drosophila melanogaster bru2 (38% identical), Drosophila melanogaster bru1 (37% identical), and 4 more. Paralogues in human: CELF6 (67% identical), CELF5 (66% identical), CELF3 (65% identical), CELF2 (47% identical), CELF1 (46% identical), RBM28 (23% identical).
Diseases named in the same sentence as CELF4 in open-access papers:
CELF4 is named in the same sentence as 34 diseases in open-access papers, as found by Europe PMC text mining. Sharing a sentence is not in itself a finding about the gene and the disease. The quoted sentences say what the papers report.
epilepsy (8 papers, 2007 to 2023). A brain disorder characterized by episodes of abnormally increased neuronal discharge resulting in transient episodes of sensory or motor neurological dysfunction, or psychic dysfunction. "Deficiencies in several RBPs other than FMRP have been associated with epilepsy, including BRUNOL4/CELF4, RBFOX1, and Pumilio2." (PMID 32988274, 2021). "Mice deficient for neuronal RNA–binding protein CELF4 have a complex neurological disorder with epilepsy as a prominent feature." (PMID 23209433, 2012). "Our GO enrichment analyses and RIP-RNA seq data suggest that early prenatal Celf4 loss from excitatory neurons may result in various synaptic defects in the SP, potentially impairing cortical excitability postnatally and causing epilepsy and depression." (PMID 37758766, 2023). "This method was used to identify differences in synchronized activity between neuronal networks from the Celf4-/- mouse model of epilepsy and wild-type (Celf4+/+) control neuronal networks (see Results)." (PMID 30273353, 2018). "Here, we demonstrate that the MEA platform, analyzed with meaRtools, can identify epilepsy-like phenotypes in neuronal networks from Celf4-/- mice." (PMID 30273353, 2018). "We demonstrate the utilization of meaRtools to successfully identify epilepsy-like phenotypes in neuronal networks from Celf4 knockout mice." (PMID 30273353, 2018). "Therefore, it is reasonable to suspect that variants in human CELF4 could contribute not only to epilepsy, but also—and maybe more so—to ASD and ID, which is corroborated by the spectrum of symptoms seen in del(18q) syndrome and specifically in the recent patient with the CELF4 translocation." (PMID 23209433, 2012). "Additional mammalian RBPs associated with epilepsy in humans and/or mice include JRK/JH8, RBFOX1, PUMILIO-2, and CELF4." (PMID 23209433, 2012). "Mice deficient for Celf4 exhibit a complex seizure disorder that includes both convulsive and non-convulsive seizures resulting from an increased neuronal excitation due to aberrant Nav1.6 (Scn8a) sodium channel activity." (PMID 31293497, 2019).
endometrial cancer (6 papers, 2020 to 2026). Primary or metastatic malignant neoplasm involving the endometrium (mucous membrane that lines the endometrial cavity). "The diagnostic accuracy of CDO1 alone and CELF4 alone in diagnosing endometrial cancer was 96.7% and 99%, respectively, with a sensitivity of 73.9% and 62.3% and a specificity of 99.3% and 98.8%, respectively." (PMID 41008854, 2025). "Methylation of CDO1 and CELF4 has been utilized in endometrial cancer detection in patients with postmenopausal bleeding or pre-menopausal abnormal uterine bleeding." (PMID 41008854, 2025). "Our study demonstrated that a combined CDO1 and CELF4 DNA methylation (epiHERA®) assay has a high accuracy (97.3%), sensitivity (84.1%), and specificity (98.8%) in diagnosing endometrial cancer." (PMID 41008854, 2025). "The DNA methylation assay of CDO1 and CELF4 (epiHERA®) on cervical scrapings has high accuracy, sensitivity, and specificity in diagnosing endometrial cancer." (PMID 41008854, 2025). "Our study demonstrated that the methylation assay of two genes, CDO1 and CELF4, is also a good option amongst the many genes that have been reported for endometrial cancer diagnosis." (PMID 41008854, 2025). "Our study aimed to determine whether cervical scrapings stored in ThipPrep®, used in conjunction with a DNA methylation assay of genes CDO1 and CELF4 (epiHERA®), are effective in diagnosing endometrial cancer." (PMID 41008854, 2025). "In other cancer types, SPON1 promotes the metastasis of human osteosarcoma, while methylated BHLHE22/CDO1/CELF4 panel could be used for endometrial cancer screening." (PMID 33860722, 2021). "Some studies showed that CELF4 was hypermethylated in endometrial cancer." (PMID 32828126, 2020). "Two hypermethylated candidate genes, namely, cysteine dioxygenase type 1 (CDO1) and CUGBP Elav-like family member 4 (CELF4), have been identified as potential biomarkers for endometrial cancer." (PMID 38107069, 2023). "Utilizing cervical scrapings as a potential genetic material, coupled with the use of DNA hypermethylation in specific genes, including CDO1, CELF4, BHLHE22, POU4F3, MAGI2, CADM1, MAL, miR124-2, ZSCAN12, and GYPC, has been investigated for endometrial cancer detection." (PMID 41008854, 2025).
cardiomyopathy (5 papers, 2021 to 2025). A disease of the heart muscle or myocardium proper. "The SNP rs1786814 in the CUGBP Elav-like family member 4 (CELF4) is associated to the propensity to develop cardiomyopathy post-anthracyclines in childhood cancer survivors." (PMID 38140053, 2023). "For the association of CELF4 rs1786814 with cardiomyopathy, the interaction between SNP and anthracycline dose was found, with p = 0.02." (PMID 36536332, 2022). "Most research was done on doxorubicin-induced cardiomyopathy and for seven genetic variants in CELF4, GPR35, HAS3, RARG, SLC22A17, SLC22A7 and SLC28A3, replication studies were performed without consistent results." (PMID 36536332, 2022). "CELF4 was first associated with anthracycline-induced cardiomyopathy in a GWAS study of childhood cancer survivors by the same group that first identified CBR3." (PMID 34575190, 2021). "In this analysis, individuals with the CELF4 rs1786814 GG genotype, who received high dose of anthracyclines (>300 mg/m2) were at 10-fold higher risk of cardiomyopathy (p < 0.001) compared to those with the GA/AA genotype and low to moderate dose (<300 mg/m2)." (PMID 34575190, 2021). "Patients with the CELF4 rs1786814 GG genotype who were exposed to anthracycline levels greater than 300 mg/m2, had a 10.2-fold increased risk of cardiomyopathy compared to patients with the GA/AA genotype and exposure to anthracycline levels of 300 mg/m2 or lower." (PMID 36536332, 2022). "GWAS in 430 childrens with (162 cases) and without (268 controls) cardiomyopathy after anthracycline therapy found that CELF4 rs1786814 polymorphism was associated with risk of cardiomyopathy." (PMID 36312261, 2022).
autism (4 papers, 2012 to 2024). Persistent deficits in social interaction and communication and interaction as well as a markedly restricted repertoire of activity and interest as well as repetitive patterns of behavior. "In lineage 1, the autism risk gene EHMT1 was highly expressed at the earliest point, followed by the sequential peak of CELF4." (PMID 39363111, 2024). "Although CELF4 shares approximately 30% of its RNA targets with FMRP, a much higher percentage of autism candidate genes, over 30%, are represented in the CELF4-bound set." (PMID 23209433, 2012).
colorectal cancer (3 papers, 2013 to 2024). A primary or metastatic malignant neoplasm that affects the colon or rectum. "Apart from this study, colorectal cancer is the most studied malignancy in relation to the CELF4 expression level and mutations." (PMID 34681716, 2021). "Additionally, CELF4 expression has been associated with poor prognosis in colorectal cancer, indicating its significance in the pathogenesis of this malignancy." (PMID 39346772, 2024). "On the other hand, the predictive study of the characteristics of RBPs in colorectal cancer highlights the significant role of CELF4 as an overexpressed transcript in highly metastatic SW620 cell lines." (PMID 34681716, 2021). "CELF4 downregulation in colorectal cancer samples is detected through analysis of the Cancer Genome Atlas database (TCGA)." (PMID 34681716, 2021). "Finally, it is worth pointing out that CELF4, TCF7L2, FTO, RUNX1, RUNX3, and CTNNB1 have all been reported to be involved in the etiology of colorectal cancer." (PMID 23626757, 2013).
depression (3 papers, 2024 to 2025). "The significant locus with the highest posterior probability of association between depression and HEM (PPH4 = 88.46%, mapped gene: CELF4) was located in the intergenic region on chromosome 18." (PMID 39588545, 2024). "We identified pleiotropic loci 11q23.2 (mapped gene: NCAM1/DRD2) and 18q12.2 (mapped gene: CELF4) in neuroticism and IBS/GERD, supporting the genetic overlap between neuroticism and depression." (PMID 40226707, 2024). "MYT1L, CELF4 and MTCH2 were given priority as novel pleiotropic genes between depression and HEM." (PMID 39588545, 2024).
Obesity (3 papers, 2012 to 2019). Accumulation of substantial excess body fat. "In either the null or haploinsufficient genetic state, CELF4 deficiency in mice causes a complex neurological syndrome with epileptic seizures as a prominent feature but which also includes hyperactivity and obesity in aging males." (PMID 23209433, 2012). "Celf4-deficient mice have additional neurological abnormalities including hyperactivity and hyperphagia-associated obesity." (PMID 23209433, 2012).
cervical cancer (1 paper, 2025). A primary or metastatic malignant neoplasm involving the cervix. "However, no robust data on CDO1 and CELF4 methylation have been reported in cervical cancer." (PMID 41008854, 2025).
chronic lymphocytic leukemia (1 paper, 2016). "For instance, SF3B1, SRSF1, U2AF65, and CELF4 are often mutated in chronic lymphocytic leukemia." (PMID 27287018, 2016).
cocaine addiction (1 paper, 2024). "Recent research that implies a relationship between Celf4 and amphetamine addiction also supports the possible connection between Celf4 and cocaine addiction." (PMID 39361596, 2024). "Moreover, rDEG rescued two intermediate regulators (Alcam and Celf4) of cocaine addiction which were missed in previous research." (PMID 39361596, 2024).
dental caries (1 paper, 2019). The decay of a tooth, in which it becomes softened, discolored, and/or porous. "In this study, CELF4 was found to be associated with S. mutans carriage and dental caries risk in primary dentition." (PMID 31148553, 2019). "However, children with certain genotypes at variants within CELF4, such as rs1539849, might be at higher risk for overeating, particularly sweetened food consumption, and consequently have an increased risk for dental caries." (PMID 31148553, 2019).
fibromyalgia (1 paper, 2025). A chronic disorder of unknown etiology characterized by pain, stiffness, and tenderness in the muscles of neck, shoulders, back, hips, arms, and legs. "Furthermore, our identification of CELF4 as a fibromyalgia risk locus provides a direct genetic rationale for exploring CELF4-based gene therapies – already under investigation for chronic pain – for fibromyalgia in particular." (PMID 41001472, 2025).
migraine (1 paper, 2025). "Our analyses revealed 283 genes, including some newly associated with migraine: MAML3, CELF4, IRX1, ASXL1, SPOCD1, CXCL, and TLR4." (PMID 41420111, 2025).
nasopharyngeal carcinoma (1 paper, 2022). A carcinoma arising from the nasopharyngeal epithelium. "Expression profiling indicates that RBM24 and CELF4 are among the few RBPs that show frequent downregulation in nasopharyngeal carcinoma (NPC) tumor tissues and various NPC cell lines." (PMID 35406615, 2022).
small bowel cancer (1 paper, 2022). "Neither KIAA1328 nor CELF4 have previously been implicated in small bowel cancer." (PMID 35922826, 2022).
cancer (12 papers, 2019 to 2024). A tumor composed of atypical neoplastic, often pleomorphic cells that invade other tissues. "The first evidence of an association between CELF4 and cancer comes from two studies on the genetic variant rs1786814, according to which the SNP contributes to chemotherapy-related cardiac dysfunction as a significant side effect of anticancer therapy." (PMID 34681716, 2021). "CELF4 as later shown to be hypermethylated in endometrial cancer, making it a viable target for cancer screening in cervical smears." (PMID 34681716, 2021). "Based on findings in other cancers, it is hypothesized that CELF4 may regulate the expression of genes involved in antigen presentation, cytokine signaling, and immune cell recruitment within the tumor microenvironment." (PMID 39346772, 2024). "Additionally, functional studies aimed at elucidating the precise mechanisms by which CELF4 regulates immune infiltration in this specific cancer type are urgently needed." (PMID 39346772, 2024). "Pedigree studies based on the UPDB have previously provided the identification of BRCA1 and BRCA2, and more recently have identified additional rare cancer predisposition variants (GOLM1; CELF4; FANCM; ERF; LRBA; FGF5) in similar sets of sampled high-risk pedigrees." (PMID 38136396, 2023). "Some identified prognostic DE RBPs have not been associated with cancers, such as CELF4, POP1, TDRD6, TDRD7, LRRFIP2, and ZC3H12C." (PMID 33224957, 2020). "A large proportion (47 RBPs) are commonly regulated in both RSCC and LSCC with several enriched for binding among DEGs (adj p < 0.05), including RBPs previously discussed in the context of CRC such MSI2, MEX3A, IGF2BP1/3, ELVAL4, and cancers in general, such as RBM47, DKC1, CELF4, ELAVL3." (PMID 32293332, 2020).
tumor (5 papers, 2020 to 2025). "The exact mechanism underlying CELF4’s influence on tumor immune infiltration in SP-EP remains elusive." (PMID 39346772, 2024). "CELF4, an RNA‐binding protein, is overexpressed due to hypomethylation, leading to aberrant splicing events that drive tumor proliferation." (PMID 40528483, 2025). "Future research is warranted to delve deeper into the specific role of CELF4 in SP-EP and its intricate interplay with the tumor immune response." (PMID 39346772, 2024). "Specifically, studies suggest that CELF4 might suppress the anti-tumor immune response by regulating immune checkpoint molecules." (PMID 39346772, 2024). "The high expression of CELF4, LPO, SLC11A1, and C7 in tumor tissues might be associated with poor prognosis, but they were not statistically significant (p-values of 0.09, 0.094, 0.06, and 0.21, respectively)." (PMID 37745305, 2023). "Further research is still needed to determine the role of CELF4 in tumours." (PMID 32828126, 2020). "The results revealed that expression levels of SLCO4C1, POU4F1, DNASE1L2, WDR72, LPO, and C7 in tumor tissues were significantly higher than those in normal tissues, while the expression differences of SLC4A4, CELF4, and SLC11A1 were not statistically significant." (PMID 37745305, 2023).
neurodevelopmental disorder (1 paper, 2024). A behavioral and cognitive disorder with onset during the developmental period that involves impaired or aberrant development of intellectual, motor, or social functions. "Celf4 has also been linked to neurodevelopmental disorders and expression is enriched in the central nervous system." (PMID 38219817, 2024).
CELF4 also shares sentences with these, for which no sentence is quoted: schizophrenia (4 papers); osteosarcoma (2); bipolar disorder (1); breast carcinoma (1); childhood cancer (1); CNS tumors (1); Endometrial Intraepithelial Neoplasia (1); gastric cancer (1); genetic disease (1); glioblastoma (1); idiopathic generalized epilepsy (1); insomnia (1); neurological diseases (1); Onset (1); psychiatric disorder (1); Seizure (1).